IL6 (interleukin 6)
Diseases named in the same sentence as IL6 in open-access papers (continued):
Sharing a sentence is not in itself a finding about the gene and the disease.
tumor (continued). "As another surrogate marker for the presence of tumor cells, we measured the levels of circulating human IL-6 and IL-10 in the NSG mice bearing BC-1-Fluc cells on day 19 after tumor inoculation." (PMID 32235878, 2020). "Specifically, sera from male tumour-bearing mice had higher levels of pro-inflammatory and chemotactic cytokines, including IL-6 (9.8-fold higher), LIF (3.5-fold higher), GCSF (2.7-fold), and MIP-1β (2.6-fold)." (PMID 32451467, 2020). "Recent studies have shown that cancer stromal fibroblasts (CAFs) in CRC are an important source of IL-6, which is critical for tumor angiogenesis." (PMID 32317968, 2020). "In contrast to tumor-infiltrating APCs, pathways related to the positive regulation of immune and defense response, including IL-8/IL-6/IL-3/CXCR4 signaling, TREM1 signaling and leukocyte extravasation pathways were downregulated in I-MDSCs." (PMID 33312958, 2020). "When correlating IL-6 with GM-CSF, there was a significant positive correlation between both cytokines in tumours which persisted in both ICC and ECC subtypes." (PMID 32747748, 2020). "The analysis of patient tumours further established clinical relevance for IL-6, GM-CSF, and MDSC in BTC." (PMID 32747748, 2020). "Preclinical research indicated that IL-6 and PD-L1 blockade combination therapy reduced tumor progression in animal models." (PMID 32847533, 2020). "In particular, IL-6 can act intrinsically on tumor cells, but it can also stimulate antitumor adaptive immunity." (PMID 32120774, 2020). "To identify additional molecules potentially involved in CPAP-mediated metastasis, we analyzed the gene expression pattern in the IL-6-treated GFP-CPAP/Hep3B cells using the human tumor metastasis RT2 ProfilerTM PCR array." (PMID 31511651, 2020). "Recent evidence suggests that, of the proinflammatory cytokines, IL-6 is a central player linking chronic inflammation to cancer by driving tumor initiation and subsequent growth and metastasis." (PMID 32832554, 2020). "Silencing of PDIA3 in GB cells resulted in reduced release by tumor cells of IL6 and COX2 and increased production of IL1β." (PMID 33153019, 2020). "Mice fed with L. helveticus R389-fermented milk and injected with BC tumor cells, showed an increased in IL-10 and a decrease in IL-6 cytokine levels in serum and mammary cells of mice, leading also to breast tumor cell inhibition." (PMID 32878124, 2020). "As such, Th17 tumor infiltration into IL-6-expressed murine PDAC tumor delayed tumor growth and improved survival due to Treg/Th17 balance shifted towards Th17, suggesting that IL-6 promotes this shift in TGF-β-rich pancreatic TME." (PMID 32823814, 2020). "As one of the most abundant cell types in the tumor microenvironment, the activated CAFs modulate the inflammatory microenvironment by secreting pro-inflammatory cytokines including IL-6, IL-8, and IL-1β and play a key role in depositing and the ECM." (PMID 33322216, 2020). "IL-6 can induce tumor cell dedifferentiation in breast, colon, and prostate cancers and regulates stemness in ovarian CSCs driven by ALDH1A1 expression." (PMID 33059744, 2020). "It has been demonstrated that IL-6 and IL-21 in the WM tumor microenvironment, induce tumor cell proliferation and IgM secretion." (PMID 32763516, 2020). "In a mice model of HCC, combinational treatment of IL-6 blockade and anti-PD-L1 presented effectiveness with smaller tumor size and longer survival time." (PMID 33292459, 2020). "On the contrary, Th2 cells secrete pro-tumoral cytokines, such as IL-4, IL-5, IL-6, IL-10, and IL-13, which induce anergy in T cells and promote the activities of tumor-promoting macrophages." (PMID 33322132, 2020).
tumor (continued). "It has also been reported that IL-8 and IL-6, important chemokines, are involved in tumor angiogenesis, growth and metastasis, and can therefore act as vital chemokines for blood vessel formation in HCC." (PMID 32938429, 2020). "Many different cell types, monocytes, fibroblasts and endothelial cells that reside around the tumor mass produce IL-6." (PMID 32751137, 2020). "Again, selective blockade of the IL-6 trans-signalling pathway by the sgp130Fc protein blocked tumour development in the APCmin/+ model and an additional mouse model of colon cancer." (PMID 32864098, 2020). "In this context, genetic knockdown of IL-6 or JAK1/2 decreased tumor cell growth in vivo and/or in vitro." (PMID 32365499, 2020). "In the PDAC microenvironment, proinflammatory cytokines secreted by tumor cells and infiltrating immune cells, such as interleukin (IL)-1β, IL-6, and tumor necrosis factor (TNF)-α, have been shown to modulate PDAC progression and immune evasion." (PMID 32929072, 2020). "In our previous studies, we found that IL-37 is a potential novel tumor suppressor by inhibiting IL-6 expression to suppress STAT3 activation and decreasing epithelial-to-mesenchymal transition." (PMID 33489865, 2020). "CAF-derived IL-6 induces the polarization of tumor-infiltrating T cells to Th17 phenotypes, thereby inducing tumor-promoting inflammation." (PMID 33050237, 2020). "Herein, we found that TENs-activated MSCs expressed higher levels of IL-6, MMP9, TGF-β, and VEGF, which have been previously shown to be associated with the pro-tumor functions of MSCs." (PMID 32903528, 2020). "In ApcMin/+ mice, three weeks treatment with 25 mg/kg quercetin (oral gavage), after tumor development, reduced muscle atrophy by lowering plasma IL-6 and muscle STAT3 activation." (PMID 33255345, 2020). "Tumor samples from the MSI-N1014 group showed markedly reduced expressions of LGR5, β-catenin, IL-6, and mTOR, but increased expression of the tumor suppressor, miR-142-3p, according to qRT-PCR analysis." (PMID 32560222, 2020). "Previous work has established that IL-6 can enhance tumor cell proliferation, survival, and chemoresistance." (PMID 32528731, 2020). "Our study also shows that the immune-related interferon, IFN-γ, and IL-6-JAK-STAT3 signaling pathways were all activated in PBRM1MUT ccRCC tumor tissues." (PMID 33177244, 2020). "Proinflammatory cytokines produced in the tumor microenvironment, including IL-1β, IL-6 and IL-8, play critical roles in promoting HCC metastasis." (PMID 32206125, 2020). "GSEA analysis showed that several gene sets associated with tumor development and metastasis, including TGF-β signaling, PI3K-AKT-mTOR signaling, and IL6-JAK-STAT3 signaling, were significantly enriched in POLR3G high expression phenotype." (PMID 33194434, 2020). "High level activated NFATc2 expression with widespread nuclear and/or cytoplasmic staining were detected in isolated or small clusters of tumor cells, accompanied by an elevated IL-6 cytoplasmic staining in the corresponding areas." (PMID 32041943, 2020). "As expected, anti-PDL1 favored the induction of an immune response within the tumor as highlighted by Tnfa, Il6, Ifng, Il2, and Tgfb induction—Ifng expression levels being significantly correlated with survival (Data not shown)." (PMID 32194552, 2020). "Abundant production of IL-6 by CAFs and other cell types (e.g., adipocytes in breast cancer) in different types of tumours indicates the importance of this factor in cancer cell biology." (PMID 33114676, 2020). "Many studies have showed that proinflammatory cytokines, such as MCP-1, IL-1B, and IL-6, induce angiogenesis and promote tumor growth, invasion and metastasis." (PMID 32548715, 2020). "Targeting a proinflammatory cytokine interleukin 6 (IL6) increases responses of tumor-specific Th1 and subsequent anti-tumor effects in tumor-bearing mice." (PMID 33344447, 2020).
tumor (continued). "Invasive phenotype of CRC tumor cells was regulated by TAM-derived IL-6 which activated the JAK2/STAT3 pathway and resulted in increased FoxQ1 expression." (PMID 33194645, 2020). "In studies using prostate specific Pten knockout mice, HFD-fed mice had greater serum IL-6 and tumor proliferation, and increased ratio of M2/M1 infiltrating macrophages." (PMID 33076397, 2020). "Intriguingly, milk fermented by Lactobacillus casei CRL 431 also retarded tumour growth in the same model of breast cancer, and serum levels of IL-6 were reduced, whereas the ratio of CD8+/CD4+ T lymphocytes was increased." (PMID 32575876, 2020). "Mean (±SD) number of tumor foci were significantly greater (Student’s t-test, t16 = −2.79, p = 0.013) in the WT (6.22 ± 0.52) than in the IL-6 KO subgroup (4.22 ± 0.49)." (PMID 32867390, 2020). "In paraneoplastic thrombocytosis, higher interleukin-6 production of the tumor modulates thrombopoietin production of the liver, which ultimately causes a significant increase in bone marrow platelet production." (PMID 33383764, 2020). "They secrete growth factors, cytokines and chemokines (e.g., EGF, FGF, HGF, TGFb, and IL-6) that stimulate also tumor growth and proliferation, as well as a more malignant phenotype." (PMID 32292409, 2020). "Voluntary running suppresses tumor growth and spread through epinephrine- and IL-6-dependent NK cell mobilization and redistribution, which modulates immunity and increases efficiency against circulating tumor cells." (PMID 31936342, 2020). "The matricellular protein CCN2, known for mediating fibrosis in various organs including the liver, has also been shown to activate HSCs and promote tumor progression via HSC secretion of the IL-6 and STAT3 in vitro." (PMID 32850829, 2020). "In particular, high IL-6 production skews macrophage activation towards a tumor-promoting phenotype, which, in turn, favors CCL20-dependent immune cell recruitment and CAC development." (PMID 32962159, 2020). "Complementing these levels of IL-6/STAT3-driven pro-tumor activities in BC is the aspect of endocrine resistance." (PMID 32605277, 2020). "In our study, we used LNCaP and LNCaP-C81 cells to study the role of dioscin in PCa; we artificially reduced the uncontrollable endogenous or exocrine IL-6 expression levels from tumor cells that interfered with the results of this study." (PMID 32792945, 2020). "Tumor cells that highly express TNF-α stimulate M1-type macrophage infiltration and secrete IL-6, which damages mucosal epithelial cells and further causes recessive hemorrhage." (PMID 33643891, 2020). "High levels of IL-6 enable the tumor cells to become resistant to both cancer immunotherapy and chemotherapy by increasing an anti-apoptotic and proliferative state in tumor cells." (PMID 32961987, 2020). "But our data showed that the Stat3-activated macrophages induced by IL-6 are closer to TAMs at the levels of promoting production of immunosuppressive factors and leading to malignant transformation of tumor cells." (PMID 33288772, 2020). "In this study, we were able to detect an increased release of the proinflammatory cytokines IL-1β and IL-6 from tumor cells treated with the highly cytotoxic NB-PDT." (PMID 32326519, 2020). "The upregulation of certain EMT protein effectors such as Snail can lead to sustained inflammation in the tumor microenvironment by the induction of IL-1, IL-6, IL-8, and cyclooxygenase-2 (COX-2) expression." (PMID 33076397, 2020). "Although a large amount of evidence points towards radiotherapy stimulating an anti-tumor immune response, radiotherapy can also unfortunately result in the secretion of immunosuppressive cytokines such as IL-6 and IL-10 from treated tumor cells." (PMID 33178210, 2020). "The expression of TIM-3 in HCC cells is accelerated tumor growth via autosecretion of IL-6, and this also increases the metastatic ability of HCC cells by promoting epithelial-mesenchymal transition (EMT)." (PMID 33425759, 2020).
tumor (continued). "In IBC, the IL-6 pathway is frequently hyperactivated; nonetheless, if suppressed, tumor cells repress E-cadherin (epithelial) expression." (PMID 32397183, 2020). "Our findings suggest that IL-6 produced in response to Tv infection of the prostate has an important effect on the tumor microenvironment by promoting progression of PCa cells following induction of M2 macrophage polarization." (PMID 32196489, 2020). "These cells showed MDSC functional characteristics and promoted tumor growth by inducing the release of the pro-inflammatory cytokine IL-6, Cox2, and VEGF." (PMID 32225076, 2020). "Combination therapy with IL-6 and PD-L1 antibody blockade can reduce tumor progression in a mouse model of pancreatic cancer." (PMID 33520714, 2020). "In this signaling cascade, NF-κB activation stimulates the production of IL-6, which is a proinflammatory cytokine that is critical for creating a suitable environment for tumor growth." (PMID 32595757, 2020). "IL-6 is produced by several immune cell types as well as tumor cells and is able to act in pro- and anti-inflammatory roles that support cancer cell proliferation, survival, metastasis, angiogenesis and immune evasion." (PMID 32595759, 2020). "For another set of animal experiment, hUCMSCs or hAMSCs (or IL-6 as the positive control in this model) was intravenously injected into the mice through tail veins on the 12th day after tumor inoculation, when the tumors nodules were observed." (PMID 30805774, 2019). "CD4+ helper T lymphocytes react to CAF secretion of CCL2, CCL5, and CCL17 along with polarizing cytokines IL-1, IL-6, IL-13, and IL-26 by switching from an anti-tumor TH1 response to a pro-tumor TH2 and TH17 response." (PMID 31058816, 2019). "Remarkably, only those PSCs located away from tumor cells, denoted as “inflammatory CAFs (iCAFs),” were proficient in secreting pro-stemness factors, including IL-6, CXCL-1, and CXCL-2, through activation of IL-1α-Janus kina (JAK)–STAT signaling." (PMID 31417869, 2019). "Within the tumor microenvironment, TAMs secrete IL-4, IL-5, and IL-6, which promote angiogenesis, matrix remodeling, and immune system suppression." (PMID 31409361, 2019). "The mechanisms of CAF-tumor cell interaction have been showed including paracrine signaling and exosomal transfer mediated by cytokines such as IL-6 and GM-CSF." (PMID 31014370, 2019). "A higher neutrophil count upstreams chemokine production: interleukin-1, interleukin-6 (IL-6), and tumor necrosis factor, therefore enabling tumor progression." (PMID 30800188, 2019). "The second wave of increased IL1β, TNFα, and IL6 expression is observed in the 5th day of tumor growth while IL10 second wave occurred two days earlier." (PMID 31712726, 2019). "MEK-I modulates in–vitro the immune micro-environment through a transcriptionally decrease of PD-L1 expression, enhance of MHC-I expression on tumor cells, increase of the production of several cytokines, like IFNγ, IL-6, IL-1β and TNFα." (PMID 31196138, 2019). "Tumor expression of IL1β and TNFα augmented within 24 h and IL6 within 12 h after the LPS treatment." (PMID 31712726, 2019). "Increased levels of IL-6 in the serum and tumor site have been demonstrated in several cancers including BC." (PMID 30658426, 2019). "The dominance of IL-11 over IL-6 as the cytokine enabling tumor outgrowth from the gastrointestinal epithelium also extends into clinically more prevalent situations that occur independently of overt inflammation and/or colitis." (PMID 30736824, 2019). "Consistently, in B16F10 tumor-bearing mice, the frequency of IL-6+, IL-21+ and IL-10+ CD4+ T cells in the draining lymph node and spleen were also increased." (PMID 31300052, 2019). "Under pathological conditions such as tissue injury or cancer, MSCs are recruited by pro-inflammatory factors, such as interleukin-1β and IL-6 secreted by injured cells or tumor cells to aid in the repair." (PMID 31014367, 2019).
tumor (continued). "To determine what downstream signals in the tumor cells responded to IL6 secretion by TAMs, we looked at ERK, Akt, and STAT3 pathway, which all have been reported to be activated upon stimulation with IL6." (PMID 30927925, 2019). "In multiple cancer types, CAFs are reported as a significant source of IL6 in the tumor microenvironment, highlighting CAF-derived IL6 as a potential link to cancer cachexia." (PMID 31058816, 2019). "For instance, IL-6 promotes hypermethylation of the miR142-3p promoter in glioblastoma cells and of certain tumor suppressor genes in oral squamous cell carcinoma." (PMID 31114509, 2019). "Abundant IL-6 released from aggressive cancer cells stimulates angiogenesis and tumor evasion from immune surveillance." (PMID 30885232, 2019). "The data indicate that immune effectors are present in NSCLC PE and suggest that the IL-6/sIL-6Rα axis is a central driver of the immunosuppressive, tumor-supportive pleural environment." (PMID 31741710, 2019). "The mRNA expression levels of COX2, TNF-α, Il-6, and Ccl2 were significantly decreased in the tumor tissues of the Ct55 knockout mice compared with those of the WT mice." (PMID 30944312, 2019). "As a further hallmark of T-cell activation upon tumor lysis, a number of cytokines were released into culture supernatants, including IFN-γ, TNF, IL-6, and IL-2." (PMID 31293575, 2019). "There are several types of DC-vaccines, being the most frequently used the reinfusion of ex vivo derived DC pulsed with tumor-associated antigens (TAAs) or tumor cell lysates and stimulated with TNF-α, IL-1β, IL-6, and prostaglandin E2 (PGE2)." (PMID 31998254, 2019). "Platelets can increase angiogenesis and stimulate tumor growth by cytokines (interleukin-6) and vascular endothelial growth factor." (PMID 31933628, 2019). "As pro-inflammatory cytokines, IL-6 and IL-17 also mediate the expression of PD-L1 in the tumor microenvironment." (PMID 30646912, 2019). "Another group showed that pro-inflammatory cytokines TNFα, IL-6, CSF-1, and IFNγ correlated with disseminated tumor cells in BC18." (PMID 30814616, 2019). "It should be mentioned that depletion of IL-6 converted tumor-derived EVs from tumor promoters to inhibitors of tumor metastasis in vivo." (PMID 31680949, 2019). "Proinflammatory cytokines released by tumor tissue and related inflammatory cells, such as IL-6 and IL-4, can affect Alb synthesis in hepatocytes, leading to reduction of Alb levels." (PMID 31814824, 2019). "CAAs also secrete several adipokines, such as TNF-α, IL-6, and IL-8, which support tumor cell growth." (PMID 31277406, 2019). "Proinflammatory cytokines, including interleukin-6, are produced by the tumor or surrounding cells and stimulate the production of acute-phase reactant proteins in the liver, such as CRP Therefore, CRP is associated with malignancy." (PMID 30974894, 2019). "This suggests that tumor cells can dampen DCs differentiation through an autocrine activation of STAT3 by IL-6." (PMID 31480382, 2019). "IL-6 inhibition increases the tumor microenvironment's sensitivity to chemotherapy and anti-angiogenic therapy and promotes tumor cell death." (PMID 31474975, 2019). "Collectively, these results indicate that IL-6 secreted from HSCs can expand the population of MDSCs within the tumor and blood to promote HCC growth." (PMID 31614930, 2019). "Activated by CD154 or IFN-γ, the CD40 pathway in tumor cells induced the production of IL-6, promoting the progression of a variety of tumors." (PMID 31708918, 2019). "IL-6 manifestation was detected in tumor cells and tumor-infiltrating leukocytes, suggesting the presence of a paracrine loop of stimulation." (PMID 31766212, 2019). "Other factors such as tumor growth factor β (TGF-β), interleukin 6 (IL-6) and various metalloproteases, are also secreted at the tumor microenvironment to promote tumor growth and metastases." (PMID 30670778, 2019).